IL6 (interleukin 6)
Diseases named in the same sentence as IL6 in open-access papers (continued):
Sharing a sentence is not in itself a finding about the gene and the disease.
asthma (continued). "Our findings provide strong evidence that the down-regulation of miRNA-221-5p increased IL-6, IL-17, IL-21 and IL-22 levels, and reduced IL-10, IL-35 and TGF-β levels in vitro model of asthma." (PMID 34863307, 2021). "Finally, the expression level of IL-6, IL-8, and IL-33 have been detected using the ELISA kits, and Pearson's correlation analysis was performed to investigate the relationship between the level of miR-3934 in PBMCs and the serum expression of those inflammatory cytokines in asthma patients." (PMID 33506046, 2021). "Cytokines (IL‐6, TNF‐α, and IL‐1β) by bronchial epithelial cells promotes the development of asthma." (PMID 34342160, 2021). "In this study, we examined the serum levels of CCL21, IL-1β, IL-6, and TNF-α in patients with asthma and healthy controls." (PMID 33503170, 2021). "IL-6, RANTES, Clusterin, MIG, BLC and MIP-1a/b have been found to exhibited raised levels in asthma." (PMID 34516405, 2021). "Here we report the mRNA expression and protein levels of pro-inflammatory and pro-fibrotic markers (IL-6, IFN-β1, CCL2/MCP-1, fibronectin 1 and type I collagen) among BSMCs groups: asthma, COPD, and healthy controls." (PMID 34512638, 2021). "In contrast, both IL-1β and IL-6 production were significantly lower in response to HDM and LPS in children with asthma." (PMID 34220812, 2021). "IL-6 and IL-1β production by PBMCs in response to HDM and LPS were impaired in children with asthma in our study." (PMID 34220812, 2021). "BSMCs treated with polyI:C, had a significant increase in mRNA expression of IL-6, IFN-β1, CCL2 compared to untreated cells and this effect was observed to a higher extent in asthma and COPD BSMCs (p < 0.05)." (PMID 34512638, 2021). "Another research showed that higher levels of IL-6 and MMP-9 were observed in asthma patients compared to the control group and in severe asthma as compared to moderate asthma." (PMID 34221070, 2021). "CS-resistant severe asthmatics typically exhibit a T2-low asthma, wherein several pro-inflammatory cytokines including IFN-γ, TNF-α, IL-6 and IL-12 mediate its pathogenesis." (PMID 34777398, 2021). "In ACO mice, there was an overlap of asthma and COPD with marked increases of total leukocytes, neutrophils, and eosinophils counts and higher levels of inflammatory cytokines (IL-4, IL-6, TNF-α, IL-1β, IL-17A, and IFN-γ) in BALF." (PMID 33869177, 2021). "As revealed by our results, the levels of pro-inflammatory cytokines IL-6, IL-17, IL-23 and TGF-β increased in the asthma model." (PMID 33645621, 2021). "Hyperleptinemia, hyperresistinemia, and lower concentrations of adiponectin, as well as elevated levels of IL-6 and reduced levels of IL-10, were found in patients with T2DM and in those with concomitant T2DM and asthma." (PMID 33520042, 2021). "We made the observation that GC insensitivity present in ASM cells derived from severe asthma was also reported to be gene-specific with CCL5, IL-6 and CCL11 being resistant to dexamethasone (or fluticasone), while CXCL10 still being repressed by either GCs." (PMID 35387008, 2021). "Our finding of a significantly lower level of IL-6 and IL-1B in response to HDM and LPS in the asthmatic group is in concordance with the previous study that reported lower expression of TLR4 in asthma." (PMID 34220812, 2021). "As we all know, molecules such as IL-4, IL-6, TNF-α, Ig-E, and Th17cell played key roles in the pathological process of asthma." (PMID 32831980, 2020). "One of the major reasons for severe asthma are Th17 cell types which differentiate from naive CD4+ cells on stimulation with IL-1β, IL-23, TGF-β, and IL-6." (PMID 32641036, 2020). "A high number of positive correlations between the assessed cytokines and CHI3L1, IL-12p40, IL-1β, IL-6, IL-8, TNF in moDCs was observed in asthma and COPD." (PMID 32842623, 2020). "Sputum IL-6 level was inversely related to FEV1 (% predicted) and positively correlated with the Asthma Control Questionnaire (ACQ) score." (PMID 32929606, 2020).
asthma (continued). "The levels of IL-6 and MCP-1 in the asthma group were significantly higher than those in the healthy control group (IL-6: P = 0.013, MCP-1: P = 0.003), while IL-17A showed an opposite trend (P < 0.001)." (PMID 32295589, 2020). "We used our method to quantify GN, GP bacteria, blaTEM gene, IL-6, and TNF-α in human BALF samples from 11 healthy subjects and 23 subjects with asthma." (PMID 32451375, 2020). "TNFα induced a robust cytokine response in HBECs and so was chosen as the stimulus for primary bronchial epithelial cells; TNFα significantly increased secretion of IL-6 and CXCL8 from both healthy subjects and asthma patients (p < 0.05 for all comparisons)." (PMID 31974640, 2020). "In summary, epithelial-derived mediators such as CCL5, IL-1, IL-8, IL-6 and TNF-α drive mesenchymal-mediated inflammation that promotes TH2, eosinophilic and neutrophilic inflammation in different asthma subtypes." (PMID 32679790, 2020). "Many of the mediators (e.g., TGF-β1/2, ET-1, TSP-1, CCL5, IL-1, IL-8, IL-6, TNF-α, BNP), highlighted in this review to drive epithelial-mesenchymal cross-talk have previously been identified in asthma pathogenesis." (PMID 32679790, 2020). "In children with asthma, DNA methylation of candidate genes (such as IL6 [IL-6] and NOS2 [inducible nitric oxide synthase]) in nasal epithelium is associated with exhaled nitric oxide (FeNO), a marker of airway eosinophilic inflammation." (PMID 31001502, 2019). "Among asthmatic patients, OX40L level positively correlated with airway inflammation, such as serum IgE, percentages of eosinophils and neutrophils, serum IL-6 and TSLP, and negatively correlated with asthma severity (ACT score) and pulmonary function (FEV1%)." (PMID 30890137, 2019). "IL-6 is crucial for DCs to trap allergens and initiate Th2/Th17-mediated airway inflammation and airway hyperresponsiveness (AHR) in asthma." (PMID 31284537, 2019). "However, an attenuated IL13 and IL6 response may have particular clinical relevance for respiratory health in endurance athletes, given their central role orchestrating the response to upper respiratory tract infections and implication in asthma." (PMID 31194785, 2019). "The antiasthma simplified herbal medicine intervention (ASHMI) alleviates asthma symptoms by modulating Group 1 cytokine (inhibition of TNF-α and IL-6) and Group 2 cytokine (inhibition of IL-17, IL-13, IL-5, and IL-4, and enhancement of IFN-γ) expression." (PMID 31284537, 2019). "Inflammatory cells contribute to the pathogenesis of asthma by secreting pro-inflammatory cytokines including TNF-α, IL-6, and IL-1." (PMID 31143692, 2019). "On the other hand, the systemic inflammation with increased production of IL-1, IL-6, or TNF-α has an effect on the various processes in asthma, such as recruitment and adhesion of eosinophil to airway epithelial cells and bronchoconstriction." (PMID 29951106, 2018). "In the present study we demonstrate that, both in steady state conditions and following acute asthma induction with low-dose HDM, the vast majority of IL-6 positive cells are leukocytes." (PMID 30534125, 2018). "Our previous reports also showed that ambient PM increases neutrophilic airway inflammation and production of inflammatory IL-6 and MIP-2/CXCL2 in a mouse model of asthma." (PMID 29882826, 2018). "However, the exact molecular mechanism of IL-6 involvement in the pathogenesis of asthma remains largely unknown and the major cellular source of pathogenic IL-6 has not been defined." (PMID 30534125, 2018). "For this purpose, we determined differential leukocyte counts and concentrations of IFN-γ, IL-5, IL-6, IL-13, and KC/CXCL1 in BALF in a mouse model of OVA-induced asthma." (PMID 29882826, 2018). "In acute model of asthma, the levels of TNF-α (p < 0.05) and IL-6 (p < 0.01) in BALF obtained from OVA-treated mice were higher as compared to control mice." (PMID 28293189, 2017).
asthma (continued). "Plasma cytokines (IL-5, IL-6), lung function (FEV1), sickness behaviour, asthma-related quality of life and self-rated health were assessed in 181 patients with allergic asthma aged 18–64 years in a one-year longitudinal study." (PMID 28915273, 2017). "In asthma/A(H1N1)pdm09 mice, IL-6 and TNF-α levels peaked at 3 days post-infection and were higher than those in all other groups." (PMID 28831046, 2017). "Changes in Th17 cells correlate with asthma induction, making it important to analyze Th-17 proteins such as TNF-α, IL-6, and IL-1β." (PMID 29151835, 2017). "In asthma model of chronic allergic airway inflammation, the TNF-α (p < 0.05) and IL-6 (p < 0.01)levels were reduced in BALF and lung homogenate on treatment with kinase inhibitor." (PMID 28293189, 2017). "In ASMCs from patients with severe asthma, TGF-β plus FCS not only induces IL6 mRNA expression and protein release but also PVT1 expression." (PMID 27484035, 2017). "The aim of the present study was to investigate two relevant cytokines, IL-5 and IL-6, FEV1 (% predicted), sickness behaviour and asthma-related quality of life as determinants of self-rated health in patients with asthma." (PMID 28915273, 2017). "Hence, IL‐6 might be a suitable target for a new approach to asthma therapy." (PMID 28474507, 2017). "The levels of inflammatory factors (IL-5, IL-6, IL-13, and TNF-α) and those of fibrosis-related proteins (basic fibroblast growth factor (bFGF), IGFBP-3, and TGF-β) were significantly higher in asthma patients than in healthy controls." (PMID 28796252, 2017). "PedsQL3.0 was used to measure the effect of asthma on QOL of children, and the correlation between IL-4, IL-6, and IL-12 levels and the lung function and QOL was measured." (PMID 28328807, 2017). "It is also unlikely that false positives would occur differentially for different tertiles of IL-6 or CRP, or by asthma/eczema diagnosis." (PMID 27476619, 2017). "Among these cytokines, IL-1, IL-6, and TNF-α are considered to be involved in various inflammatory diseases including asthma and chronic pulmonary disease (COPD)." (PMID 28116321, 2016). "The IL-6 high group was more common in the cohort with severe asthma and had lower FEV1, worsened asthma control, and more frequent exacerbations." (PMID 27610226, 2016). "The four asthma-related biomarkers are periostin and interleukin 13 (IL-13), chitinase-like protein (YKL-40), and interleukin 6 (IL-6)." (PMID 26673104, 2015). "The levels of interleukin IL-4, IL-6 and IFN-γ, which are involved in OVA-induced asthma, in the bronchoalveolar lavage fluid (BALF) and the IgE level in the serum were examined by enzyme-linked immunosorbent assay (ELISA)." (PMID 26132811, 2015). "Sputum IL-6 and CCL2 levels were significantly higher in subjects with COPD than in subjects with asthma, with ROC AUCs of 0.86 (95% CI, 0.81-0.92; P < .0001) and 0.69 (0.61-0.77; P < .0001), respectively." (PMID 25129678, 2015). "Our results show that inhibition of BET bromodomains can reduce both aberrant ASM cell proliferation and expression of cytokines from patients with severe asthma by reducing Brd4 binding to the promoter regions of IL8 and IL6 genes." (PMID 25697361, 2015). "IL-5 regulates the development, activation, migration, and survival of eosinophils and stimulates the expression of IL-6, which is a T- and B-cell growth factor that produces IgE and regulates CD4+ T-cell function to induce asthma." (PMID 25658604, 2015). "In previous studies Gal was shown to be an anti-inflammatory compound that inhibits Interleukin-6 (IL6) signaling in a Janus Kinase/Signal Transducer and Activator of Transcription (STAT)—dependent manner and reduces experimental asthma." (PMID 26076475, 2015). "The sputum inflammatory mediator profiles were distinct with increased TH2 (IL-5, IL-13, and CCL26) and TH1 mediators (CXCL10 and 11) in severe asthma compared with COPD and increased IL-6, CCL2, CCL3, and CCL4 in COPD compared with severe asthma." (PMID 25129678, 2015).
asthma (continued). "The current study aimed to investigate the expression of IL-4 and IL-13, as well as IL-6, IL-10 and TNF-α, in the sheep model of asthma following allergen challenge of the airways." (PMID 26362930, 2015). "Strong pro-inflammatory and Th2-associated cytokines; including interleukin-1β (IL-1β), IL-4, IL-5, IL-6, IL-9, IL-13, IL-17, IL-25 and tumor necrosis factor α (TNF-α) were reported to enhance asthma." (PMID 24735374, 2014). "The cytokine IL-6 was recently shown to induce migration of bronchial epithelial cells in PI3K/Akt/GSK-3β/β-catenin dependent manner suggesting that this pathway may be contributing to the mesenchymal population of cells often found in asthma through induction of EMT signals." (PMID 25413472, 2014). "In mild asthma, Il10 showed the largest change in expression followed by II5, II4, Tnfα, Il6, Il2, Il13, and Ifnγ, respectively." (PMID 23781124, 2013). "IL2, IL4, IL5, IL6, IL13, and TNFαhave been reported to enhance asthma in humans, and Th1 cells have been shown to suppress Th2 cells through the release of IFN-γ." (PMID 23781124, 2013). "Angiogenesis antibody arrays revealed that CM of BSMC from asthma patients contained significantly higher levels of angiogenin, ENA-78, GRO-α, IL-6, IL-8 and MCP-1." (PMID 24339939, 2013). "We monitored production of interleukin-6 (IL-6) and interleukin-8 (IL-8) (alias CXCL8), two pro-inflammatory cytokines produced by airway cells that are relevant in asthma pathogenesis." (PMID 23369242, 2013). "The patients with severe-critical asthma had higher serum PCT levels and IL-6 levels compared with those with mild-moderate asthma (p < 0.05)." (PMID 24341820, 2013). "By contrast, in non-SLIT group, asthma symptom score, lung function, Th17 cell percentages, IL-6 and IL-17 levels have all significantly improved, but on the whole lower than SLIT group (p < 0.05)." (PMID 41630053, 2026). "In the pediatric cohort, non-T2 asthma was characterized by higher circulating IL-2, IFN-γ, IL-6, and IL-17A compared with T2-high disease, whereas these same Th1/Th17-associated and pro-inflammatory cytokines were uniformly low and non-discriminatory in adults." (PMID 41601686, 2026). "Moreover, 1,8-cineole downregulated the levels of pro-inflammatory cytokines, such as IL-1β, IL-4, IL-6, IL-13, IL-17A, and TNF-α, in the BALF of animal asthma models sensitized with ovalbumin, house dust mite, and cigarette smoke." (PMID 40244178, 2025). "Conversely, nonallergic asthma, affecting 10–40% of asthma cases, is characterized by an acute inflammatory response involving cytokines such as IL-1, IL-6, IL-8, and TNF-α, leading to neutrophil infiltration and airway inflammation." (PMID 40410722, 2025). "Urinary 8-OHdG, white blood cells and differential counts, platelets count, hsCRP, IL-6, and IL-8 in the asthma group were not significantly higher than controls during the same period." (PMID 40217808, 2025). "Lung and circulating IL-6 levels are also up-regulated in other asthma phenotypes, for example, in non-allergic asthma and patients with predominantly neutrophilic or mixed granulocytic inflammation." (PMID 39714726, 2025). "The main molecular pathways of asthma include T2 inflammation, mediated by Th2 and ILC2 cells, eosinophils, and the cytokines IL-4, IL-5, and IL-13, as well as non-T2 inflammation, mediated by neutrophils, macrophages, and the cytokines IL-1, IL-6, and IL-17." (PMID 40136501, 2025). "In our study, the IL-6 level during the pollution period was insignificantly higher than the low-pollution period in patients with asthma and not different from healthy control in both seasons." (PMID 40217808, 2025). "miR-221 regulates airway smooth muscle cell proliferation and IL-6 production, downregulation of the miR-200 family permits ZEB1/2 upregulation, driving epithelial–mesenchymal transition during airway remodeling in asthma." (PMID 40722500, 2025).
asthma (continued). "Lung function was lowest in non-lean, high IL-6 patients with asthma, with similar trends in non-lean (BMI ≥ 25) patients without asthma." (PMID 39714726, 2025). "Future research should focus on the high IL-6 asthma population that is non-obese and free from metabolic dysfunction to fully understand the additional biological mechanisms at play." (PMID 39714726, 2025). "Our biomarker analysis study also indicated that serum concentrations of IL-6 and the annual exacerbation ratio were significantly higher in overweight asthma patients than those who were not overweight." (PMID 40589493, 2025). "In addition to Th1/Th2 cytokines, IL-6, CD40L, TNF-α, IFN-γ, MIP-3α, and IL-10 contribute to asthma-related inflammation." (PMID 41155381, 2025). "Moreover, in OVA-induced murine asthma models, baicalin administration significantly suppressed NFκB activation and downstream cytokine production, including CCR7, CCL19, CCL21, and IL6, leading to reduced lung tissue inflammation." (PMID 40598285, 2025). "DiABZI induced an increased release of lactate dehydrogenase (LDH), IFNα, IFNβ, IFNλ, CXCL10, IL‐6 and TNFα protein and overexpression of MUC5AC transcript in healthy epithelial cells sensitized with HDM, and less in epithelial cells from patient with asthma." (PMID 39466641, 2025). "This type of asthma, also termed “non-eosinophilic asthma” or “neutrophilic asthma,” involves IL-6 produced by airway epithelial cells and neutrophils, IL-1β produced following inflammasome activation, and TGF-β produced by neutrophils and eosinophils." (PMID 38629073, 2024). "In contrast, serum IL-6 and IL-8 were significantly lower in asthmatics at 12 months compared to baseline, while airway macrophages spontaneously produced more TNF-α, IL-6, IL-1β, and IL-10 at 12 months in the asthma group compared to baseline and controls." (PMID 39200943, 2024). "Additionally, we examined the levels of inflammatory cytokines in sputum and found that IL‐5, IL‐6, IL‐8, TNF‐α, IFN‐γ, CCL17, CCL22, CXCL10, CCL4, CCL2, IL‐4, IL‐13, and CCL26 were significantly lower in stable asthma than in acute asthma." (PMID 39508721, 2024). "C. chinensis seed methanol extract can reduce IL-6, TNF-α, NF-κB, COX-2, and IL-1β in asthma." (PMID 39263346, 2024). "In addition, it significantly attenuated the symptoms of asthma attacks, reduced the number of macrophages, lymphocytes, neutrophils, and eosinophils in BALF and inflammatory cytokines, including IL-1β, IL-5, IL-6, and IL-13." (PMID 38579176, 2024). "In “type 2-low” asthma, airway inflammation is mediated by IL-1β, IL-6, and neutrophils, with a lack of Th2 response and low frequencies of blood sIgE antibodies." (PMID 38629073, 2024). "In our study, TNF-α and IL-6 levels in BALF and lung tissues of the respective group were examined to reveal whether L6H21 reduces IL-6 and TNF-α levels in mouse asthma model, and positive results were identified in the L6H21 treatment group." (PMID 38245791, 2024). "The exceedingly low levels of IL-6 are not surprising in the severe asthma group given the neutrophil predominance." (PMID 38534377, 2024). "Utilizing 26 genetic instruments for IL6R blockade, this study offers evidence suggesting that downregulation of IL6 signaling pathways may confer protective effect against the development of COPD and asthma." (PMID 38898459, 2024). "When airway epithelial cells were exposed to plasma from the obese non-asthmatic group, IL-8, CCL20, G-CSF, and IL-6 levels decreased, with a similar trend in the obese type 2-low asthma group." (PMID 39200943, 2024). "Likewise, in children with exacerbated and controlled asthma, miR-181a expression negatively correlated with serum levels of TNF-α, IL-1β, and IL-6." (PMID 38337625, 2024). "In serum and BALF, IL-6 expression in the asthma group increased but was not significant compared to the control group (P > 0.5)." (PMID 38273268, 2024).